LHX1 (LIM homeobox 1)
Description:
Potential transcription factor. May play a role in early mesoderm formation and later in lateral mesoderm differentiation and neurogenesis.
Synonyms: LIM-1; LIM1
Tractability: No criterion of Open Targets' tractability assessment is met for any kind of drug.
Gene: Protein-coding gene on chromosome 17 (36,936,784 to 36,944,612, forward strand). Ensembl gene ENSG00000273706.
Subcellular location: Nucleus
Subcellular location (Human Protein Atlas): Nucleoplasm; Golgi apparatus; Nuclear membrane
Pathways (Reactome):
Developmental Biology: Formation of intermediate mesoderm; Formation of the nephric duct; Nephron development
Gene Ontology:
Molecular function: protein binding; sequence-specific double-stranded DNA binding; DNA-binding transcription factor activity; DNA-binding transcription factor activity, RNA polymerase II-specific; RNA polymerase II transcription regulatory region sequence-specific DNA binding; cis-regulatory region sequence-specific DNA binding; DNA binding; sequence-specific DNA binding; zinc ion binding
Biological process: anatomical structure formation involved in morphogenesis; anatomical structure morphogenesis; animal organ morphogenesis; anterior/posterior axis specification; anterior/posterior pattern specification; cell-cell signaling; cerebellar Purkinje cell differentiation; cerebellar Purkinje cell-granule cell precursor cell signaling; cerebellum development; cervix development; comma-shaped body morphogenesis; dorsal spinal cord interneuron posterior axon guidance; dorsal/ventral pattern formation; ectoderm formation; embryonic pattern specification; embryonic retina morphogenesis in camera-type eye; embryonic viscerocranium morphogenesis; endoderm formation; epithelium development; forebrain regionalization; gastrulation with mouth forming second; head development; kidney development; lateral motor column neuron migration; motor neuron axon guidance; and 47 more
Cellular component: chromatin; nucleus; protein-containing complex; transcription regulator complex
Genetic constraint (gnomAD): Loss-of-function variants: 9 observed, 28.43 expected, observed/expected ratio (o/e) 0.32, 90% interval 0.19 to 0.55. The upper end of that interval is the gene's LOEUF score, 0.55, which puts it in group 2 of 6, group 1 being the genes least tolerant of losing a copy. Missense variants: 442 observed, 528.16 expected, observed/expected ratio (o/e) 0.84, 90% interval 0.77 to 0.9. Synonymous variants: 251 observed, 237.26 expected, observed/expected ratio (o/e) 1.06, 90% interval 0.95 to 1.17.
Homologues: Orthologues: chimpanzee LHX1 (99% identical), dog LHX1 (99% identical), guinea pig LHX1 (99% identical), macaque LHX1 (99% identical), pig LHX1 (99% identical), mouse Lhx1 (99% identical), rat Lhx1 (99% identical), tropical clawed frog lhx1 (93% identical), rabbit LHX1 (58% identical). Paralogues in human: LHX5 (74% identical), LHX4 (36% identical), LHX3 (35% identical), ZFHX3 (29% identical), LMX1A (28% identical), ZFHX4 (28% identical), LMX1B (27% identical), LHX6 (25% identical), LHX2 (24% identical), LHX8 (22% identical), LHX9 (22% identical), ZFHX2 (22% identical), and 8 more.